CD44 (CD44 molecule (IN blood group))
Diseases named in the same sentence as CD44 in open-access papers (continued):
Sharing a sentence is not in itself a finding about the gene and the disease.
tumor (continued). "While normal tissues (such as colonic mucosa) do not express variant isoforms of CD44, tumours seem to perform a wide variation of CD44 isoforms." (PMID 23151220, 2012). "Interestingly, these CSC-like cells can proliferate without differentiation, have characteristics of tumor-initiating cells and express tumor cell markers (CD44+ and CD24−) characteristic of CSCs." (PMID 23185620, 2012). "Although the interaction of CD44 with HA is clearly important in the context of cancer, the role of these molecules in tumor growth and metastasis needs further investigation to understand the sometimes contradictory results regarding the nature of this interaction." (PMID 22916191, 2012). "However, since nearly 80% or more of MDA-MB-231 cells express CD44 in culture, most cancer cells in the tumor will have CD44 expression as was apparent from the SPECT imaging data." (PMID 22937154, 2012). "The extracellular matrix can influence the expression of CD44 isoforms and thereby may facilitate tumor invasion." (PMID 22895640, 2012). "Furthermore, FACS analysis of tumors excised and digested revealed that both types of neoplasia contained a comparable CD44+CD24− cell population." (PMID 22328933, 2012). "Furthermore, reducing either CD44 or CD147 expression effectively reduced CaP tumor growth, enhanced the response to DTX, reduced angiogenesis and induced apoptosis in vivo." (PMID 22870202, 2012). "Moreover, the expression of miR-34a antagomirs in CD44- prostate cancer cells promoted tumor development and metastasis." (PMID 22417299, 2012). "CD44 is a receptor for hyaluronic acid (HA), which plays an important role in cell migration, tumor growth and progression through its affinity for HA, possibly also through its affinity for other ligands such as osteopontin, collagens, and matrix metalloproteinases (MMPs)." (PMID 22606006, 2012). "CD44+ cells can effectively form a sphere in vitro and initiate a tumor in vivo." (PMID 22895640, 2012). "In addition, interaction of the HA receptor, CD44, with low molecular weight forms of HA induces urokinase expression and facilitates urokinase-dependent tumor cell invasion, in vitro." (PMID 23145170, 2012). "Lung metastasis was observed in mice injected with CD44/Scal+ tumor cells." (PMID 22277639, 2012). "Moreover, microscopic analysis of the xenografts showed that CD44+ EOC cells were able to recapitulate the morphology of the original tumor." (PMID 21904548, 2011). "We can speculate, that in cancer patients with high sCD44, tumor cells have acquired resistance to its inhibitory effects, while shedding of cell-surface bound CD44 confers significant selective advantage in tumor microenvironment." (PMID 22216242, 2011). "Supporting this thesis, Du's group has shown that CD44 could be considered as an important marker in CCSCs that give rise to spheres in vitro and to a xenograft similar to the original tumor in vivo." (PMID 24212791, 2011). "In these tumors, tumor-forming cells in vivo are restricted to CD44-positive tumor cells." (PMID 21915300, 2011). "Nevertheless, the same study did indicate that the prevalence of CD44+CD24− tumor cells might favor metastatic disease." (PMID 24212957, 2011). "However, other workers detected no significant enrichment of ALDH1+ tumour cells or even a reduction of CD44+/CD24− tumour cells after PST." (PMID 21559013, 2011). "In addition, CD44 has been identified as a specific marker of cancer stem cells and of tumor cells undergoing an epithelial-mesenchymal transition (EMT)-like process." (PMID 22069487, 2011). "Similar treatment-related decreases in CD44+ tumor cells were also noted." (PMID 21912653, 2011). "The cases with increased CD44+/CD24− tumour cell populations after PST showed high Ki-67 proliferation index in post-chemotherapy specimens (P=0.038) and tended to show high post-neoadjuvant therapy pathologic T (ypT) stage (P=0.091) and ER negativity (P=0.067)." (PMID 21559013, 2011).
tumor (continued). "Using a xenograft tumor model, we demonstrated that following injection of double positive CD44+/Tomato+ cells, the newly formed tumor originating from these double positive cells is characterized by CD44− cells, which maintain the expression of the fluorescent protein Tomato." (PMID 21904548, 2011). "To determine whether CD44+/CD24− tumour cell proportion and ALDH1 positivity were predictive factors of pCR, we performed logistic regression analyses." (PMID 21559013, 2011). "IHC analysis of tumor samples confirmed CD44 protein expression for all patients." (PMID 24212639, 2011). "We therefore, examined the metastatic tumor cell lines for their surface expression of CD44." (PMID 24212937, 2011). "CD44+ sub-population of GC cell lines shows characteristics of tumour-initiating cells." (PMID 21829201, 2011). "This broad pattern of CD44 expression across various tumor types could lead to inaccurate analyses of CD44+ tumor populations." (PMID 21858056, 2011). "However, neither the basal secretion of IL-6 nor the induced secretion of IL-6 by PGE2 in fibroblasts correlated with fibroblast tumor promoting ability in vivo or their ability to expand CD44+/CD24−/EpCAM+ cells in vitro." (PMID 21957456, 2011). "Both CD44 and RHAMM have been implicated in tumour cell biology and tumour progression." (PMID 21429221, 2011). "The CD44 molecule and several of its isoforms have attained a lot of focus during the last decades, being described as aberrantly expressed in cancer cells and involved in metastatic spread in various tumor forms." (PMID 21957977, 2011). "With regard to the changes of CD44+/CD24− tumour cell populations, the patients with the increase of CD44+/CD24− tumour cell populations tended to have shorter DFS times than the remaining patients irrespective of PST regimen, although they were not statistically significant." (PMID 21559013, 2011). "Studies found that oncostatin M and transforming growth factor 1 (TGF1) could mediate the binding of HA to CD44 in tumor cells originated from lung epithelia, leading to the glycosylation and phosphatization of CD44." (PMID 21294926, 2011). "CD44 is involved in pathological angiogenesis, as its expression is elevated in tumor vasculature, and CD44 expression can be induced in cultured ECs by angiogenic growth factors Furthermore, CD44 knockout mice show reduced vascularisation of tumor xenografts and Matrigel plugs." (PMID 22216242, 2011). "Specifically, cells with CD44+CD24low phenotype, which yielded tumor formation with as few as 100 cells (compared with that the control), were found significant increased when cells were treated with transforming growth factor-beta or were overexpressing the key EMT inducers, Snail and Twist." (PMID 21284870, 2011). "Furthermore, in vivo targeting of CD44 by siRNA resulted in anti-tumor activity in both colon cancer and leukemia xenografts." (PMID 21541039, 2011). "As basal-like tumours are enriched with CD44+/CD24− or ALDH1+ tumour cell population, as shown in this study, one may expect that the cases with increased CSC population after PST were mostly chemoresistant basal-like subtype and thus, show wore prognosis." (PMID 21559013, 2011). "This illustrates a plasticity of CD44 isoform expression possibly dependent on growth conditions, which might be assigned to in vivo tumor growth as well." (PMID 21957977, 2011). "However when CD133 populations were analyzed in CD44 by surface vimentin sorting, we found a subpopulation of cells for each tumor cell type that expressed all three surface markers." (PMID 24212937, 2011). "CD44 expression was predominantly localised to the membrane of tumour epithelial cells." (PMID 21829201, 2011). "Not the splicing variant but CD44 extracellular domain cleavage is considered to play a critical role in CD44-madiated tumor cell migration by regulating the interaction between CD44 and extracellular matrix." (PMID 21473743, 2011).
tumor (continued). "In addition, the cases with increased CD44+/CD24− tumour cell populations after PST were found to have high Ki-67 proliferation index in post-chemotherapy specimens." (PMID 21559013, 2011). "The nonrandom occurrence of tumors of particular phenotypes in the different clusters suggests that CD44 may be part of the tumor progression program that drives development to distinct molecular subtypes or, alternatively, a consequence of this process." (PMID 21957977, 2011). "Importantly, prospective knockdown of CD44 in Du145 cells greatly inhibits Du145 cell proliferation and tumor regeneration." (PMID 21935404, 2011). "However, other groups have shown that CD44 is expressed by a majority of tumor cells in HNSCC and also by normal HN epithelium as well as benign lesions of the head and neck." (PMID 24212622, 2011). "CD44 and HA mediate the overexpression and activation of integrin as well as the adhesion of tumor cells to epithelia, and enhance the migration and metastasis of tumor cells." (PMID 21294926, 2011). "We further classified the cases into negative (<5% n=80) and positive (⩾5% n=12) groups for ALDH1 and found that the ALDH1-positive group contained a higher proportion of CD44+/CD24− tumour cells than the ALDH1-negative group (median (interquartile range), 45% (20–70%) vs 5% (1–30%); P=0.003)." (PMID 21559013, 2011). "Interestingly, the resulting mesenchymal tumor cells had a CD44+CD24−/low phenotype with the ability to reestablish an epithelial tumor and increased drug resistance, which is consistent with breast CSCs." (PMID 21643534, 2011). "It is intriguing to speculate that proteolytic processing of CD44 accounts for any additional invasiveness of the tumor lines." (PMID 24212937, 2011). "In an experiment, the authors found that HA containing material could inhibit the invasion of the CD44 positive tumor cells." (PMID 21749678, 2011). "Further to previous studies, we have found a significant inverse relationship between the two phenotypes under investigation, BRCA1 and CD44+, indicating that these tumour cells may be a subpopulation of tumourigenic cells." (PMID 23508738, 2011). "However, with numerous studies finding that disruption of the HA-CD44 interaction decreases the proliferative and metastatic behavior of tumor cells, CD44 still remains a valid target for anti-cancer therapy." (PMID 21541039, 2011). "High levels of CD44 expression on tumor cells is sufficient to establish metastatic behavior." (PMID 22216242, 2011). "We examined their expression in different CD44 subpopulations of tumor cells by flow cytometry." (PMID 21858056, 2011). "CD44 is also networked to many signaling cascades that mediate tumor-enhancing functions." (PMID 21124918, 2010). "Importantly, when as few as 100 cells were implanted, only CD24−/low/CD44+ populations gave rise to tumours." (PMID 19997106, 2010). "Moreover, when we transplanted both populations of 1 × 102 HCC1954-Luc, we found that tumours were generated only by the CD24−/low/CD44+ population (n=6)." (PMID 19997106, 2010). "Since PCBP1 was a negative regulator of CD44 v6 expression and tumor invasion, we further examined whether a correlation of the expression status of PCBP1 and CD44 v6 exists in primary HCCs." (PMID 20361869, 2010). "The variant isoform CD44 v6 has attracted increasing interest since the demonstration 1 decade ago that the transfection of splice variant CD44 v4-v7 conferred metastatic potential on cells of a nonmetastatic rat tumor cell line." (PMID 20361869, 2010).
tumor (continued). "For instance, breast cancer cells expressing either no or low levels of single chain sialoglycoprotein CD24 in combination with CD44-positivity have been identified as CSCs, whereas in pancreas and colon, the CD24high cells were shown to contain the tumor-initiating fraction." (PMID 21311095, 2010). "For unsorted cells of H1299, tumor initiation could be achieved by 200,000 cells (3/4 mice), while with CD44+ cells, tumors were initiated by 10,000 (1/4 mice), 50,000 (3/4 mice) and 100,000 cells (4/4 mice)." (PMID 21124918, 2010). "Elevated intensities of CD133 and CD44 proteins in tumour spheroid cells are shown as examples." (PMID 20332776, 2010). "This could also indicate that only a portion of the CD44+ cells were required for tumor initiation, and that the increasing tumorigenecity of CD44+ cells was due to in vivo enrichment of CSC." (PMID 21124918, 2010). "Moreover, the CD44+/CD24−/ALDH1+ phenotype identified a highly tumourigenic cell population that was able to form tumours from as few as 20 cells." (PMID 20010944, 2010). "Based on their similar adhesive functions, LYVE1 and CD44 may both contribute to metastatic spread of cancer cells since HA is more abundant in the surrounding stroma than in the tumor itself." (PMID 20374665, 2010). "We have also shown that the CD44+/CD133+ tumorsphere-forming and tumor-initiating cells have high Bcl-2 and loss of miR-34 expression, indicating that miR-34 and its target Bcl-2 might be involved in cancer stem cells." (PMID 19714243, 2009). "At this period of complete remission, human CD44 transcripts are detected by semiquantitative nested RT–PCR, in the fat pads at the site of the tumour graft (detection threshold huCD44+ cells: one in every 107 cells), showing that at least a fraction of CD44+ cells were resistant to AC." (PMID 19240712, 2009). "Thus, our data demonstrate that the CD44+/CD133+ double-positive MiaPaCa2 cells are enriched with tumor-initiating cells or cancer stem/progenitor cells capable of self-renewal, but the CD44−/CD133− double-negative population contains no such cells." (PMID 19714243, 2009). "CD44 was strongly expressed on the cell surface of all tumor cells in all cases of HNSCC samples." (PMID 19602232, 2009). "In this perspective, it had been postulated that CD44/MMP-9 complex formation on the cell surface might signify as a novel motility-enhancing signal for tumor cells which eventually contributes their invasiveness." (PMID 19290049, 2009). "Our results also demonstrate that there may be a potentially new subpopulation (CD24+/CD44+) of tumor initiating cells in HNSCC." (PMID 19602232, 2009). "CD44 is involved in several processes, including tumour cell proliferation, adhesion and invasion." (PMID 19240712, 2009). "The overexpression of uPA, CD44 and MDR1 was found in most primary and matched metastatic lesions of EOC, and was significantly associated with tumour stage, grade, residual disease status, relapse and presence of ascites (P<0.05), but not with histology type (P>0.05)." (PMID 19603017, 2009). "The presence of CD44+ cells during tumour remission is confirmed by IHC analysis." (PMID 19240712, 2009). "Thus, we propose that CD44+CD24− prostate cells are stem-like cells responsible for tumour initiation and we provide a genomic definition of these cells and the differentiated cells they give rise to." (PMID 18268494, 2008). "Some CD44 isoforms have been found to play an essential role in tumor progression." (PMID 18350162, 2008).
tumor (continued). "Moreover, while one mouse injected with CD44+CD24+ cells formed a tumour in a similar time frame as mice injected with CD44+CD24− cells, the other two mice that formed tumours had an approximately 1 month longer latency period." (PMID 18268494, 2008). "Because we found a decrease in CD24a gene expression in the original 0_A1 tumor and in all cell lines derived from this tumor, we examined whether these cells contain a distinct CD44+/24-/low population." (PMID 18394172, 2008). "In 12% (28/240) of the tumors, the majority (> 50%) of tumor cells was CD44+/CD24-." (PMID 18559090, 2008). "The CD44+/CD24- phenotype was clearly related to certain tumor biological characteristics." (PMID 18559090, 2008). "This motivated further analysis of the prevalence of CD44+/CD24- cells in different tumor subtypes." (PMID 18559090, 2008). "CD44 expression in normal mammary gland, benign and malignant tumours." (PMID 17222331, 2007). "CD44 mediates hyaluronic acid (HA)-dependent cell adhesion: besides promoting invasion, this interaction also supports neoangiogenesis that indirectly stimulates tumour cell proliferation." (PMID 17222331, 2007). "The binding of HA to CD44 stimulates cytoskeleton-mediated tumor cell migration." (PMID 18096084, 2007). "The inverse relationship deriving from the results of the current investigation is present in two different sites: intratumoral with high CD44 expression in the tumour cells together with a low number of VEGFR-3 expressing lymphatics, and extratumoral showing the opposite." (PMID 17222331, 2007). "Also, note that the parental and tumor-derived variants of MDA-MB-231 and MDA-MB-436 had similar CD44+/CD24- subpopulations." (PMID 17062128, 2006). "HGF can promote cell adhesion by up-regulating CD44 in tumor cells and our data suggest that a similar relationship may exist in the testis." (PMID 16336681, 2005). "Since shed membrane vesicles exhibit molecules with biologic activity (such as Fas ligand, mdr 1, CD44, and autoreactive tumour antigens), the ability of these shed membrane vesicles to modulate lymphocyte and monocyte functions have been analysed in several tumour models." (PMID 15655551, 2005). "In these studies, tumour adhesion appeared to precede dissagregation of the mesothelial monolayer, and could be partially blocked by pretreatment with anti-CD44 and anti-β1 antibodies." (PMID 15054468, 2004). "Suppression of tumour formation by a human sCD44 fusion protein has again been demonstrated lately, and a soluble CD44-immunoglobulin fusion protein was able to block the migration of a CD44H-transfected human melanoma cell line across a hyaluronate-coated surface." (PMID 19570245, 2002). "Indeed, sCD44 transfection was subsequently shown to prevent hyaluronate-mediated clustering of CD44 on tumour cell surface." (PMID 19570245, 2002). "Determining the expression of CD44 or CD44v6 in a primary STS could be a valuable tool for selecting the group of patients who might benefit from intensified local tumour treatment." (PMID 11161384, 2001). "In diploid tumours the CD44 expression was correlated with low S-phase fraction (P = 0.001)." (PMID 11161384, 2001). "95% of the tumours expressed CD44 and CD44v6 was detected in 57%." (PMID 11161384, 2001). "CD44 isoforms CD44v3, CD44v5, CD44v6 and CD44v7-8 were detected in 26% (41 out of 156), 31% (48 out of 156), 22% (35 out of 156) and 15% (23 out of 156) of the tumour samples respectively." (PMID 9569051, 1998). "Furthermore, novel therapeutic strategies are being explored that leverage CSC surface markers in combination—for example, bispecific antibodies targeting both CD44 and the tumor stroma or CAR-T cells engineered to recognize CSC markers in conjunction with immunosuppressive cues within the TME." (PMID 40759634, 2025). "Furthermore, functional assays may help clarify the role of CD44 variations in tumor aggression and therapy resistance." (PMID 40363706, 2025).